VPS54 (VPS54 subunit of GARP complex)
Description:
Acts as a component of the GARP complex that is involved in retrograde transport from early and late endosomes to the trans-Golgi network (TGN). The GARP complex is required for the maintenance of the cycling of mannose 6-phosphate receptors between the TGN and endosomes, this cycling is necessary for proper lysosomal sorting of acid hydrolases such as CTSD. Within the GARP complex, required to tether the complex to the TGN. Not involved in endocytic recycling.
Synonyms: HCC8; PPP1R164; SLP-8p; VPS54L; WR; hVps54L
Tractability: PROTAC: ubiquitination databases record sites on it; its protein half-life has been measured.
Gene: Protein-coding gene on chromosome 2 (63,892,146 to 64,019,476, reverse strand). Ensembl gene ENSG00000143952.
Subcellular location: Golgi apparatus, trans-Golgi network; Membrane
Subcellular location (Human Protein Atlas): Golgi apparatus; Nucleoplasm
Pathways (Reactome):
Vesicle-mediated transport: Retrograde transport at the Trans-Golgi-Network
Gene Ontology:
Molecular function: protein binding; syntaxin binding
Biological process: lysosomal transport; retrograde transport, endosome to Golgi; Golgi to vacuole transport; apoptotic DNA fragmentation; astrocyte differentiation; cellular response to progesterone stimulus; gene expression; homeostasis of number of cells; in utero embryonic development; intracellular calcium ion homeostasis; intracellular protein localization; L-glutamate import; limb development; limb morphogenesis; microglia differentiation; mitochondrion organization; motor behavior; motor neuron apoptotic process; negative regulation of motor neuron apoptotic process; neural tissue regeneration; neuroinflammatory response; neuromuscular synaptic transmission; neuron apoptotic process; neuron projection morphogenesis; positive regulation of membrane potential; and 20 more
Cellular component: GARP complex; Golgi apparatus; perinuclear region of cytoplasm; trans-Golgi network; membrane; trans-Golgi network membrane; cytoplasm; cytosol; mitochondrion; synapse
Genetic constraint (gnomAD): Loss-of-function variants: 32 observed, 92.38 expected, observed/expected ratio (o/e) 0.35, 90% interval 0.26 to 0.47. The upper end of that interval is the gene's LOEUF score, 0.47, which puts it in group 2 of 6, group 1 being the genes least tolerant of losing a copy. Missense variants: 910 observed, 972.92 expected, observed/expected ratio (o/e) 0.94, 90% interval 0.88 to 0.99. Synonymous variants: 311 observed, 338.7 expected, observed/expected ratio (o/e) 0.92, 90% interval 0.84 to 1.01.
Homologues: Orthologues: chimpanzee VPS54 (99% identical), macaque VPS54 (97% identical), pig VPS54 (97% identical), dog VPS54 (97% identical), rabbit VPS54 (96% identical), mouse Vps54 (93% identical), rat Vps54 (92% identical), tropical clawed frog vps54 (78% identical), guinea pig VPS54 (72% identical), zebrafish vps54 (68% identical), Drosophila melanogaster scat (34% identical), Caenorhabditis elegans vps-54 (26% identical).
Diseases named in the same sentence as VPS54 in open-access papers:
VPS54 is named in the same sentence as 17 diseases in open-access papers, as found by Europe PMC text mining. Sharing a sentence is not in itself a finding about the gene and the disease. The quoted sentences say what the papers report.
motor neuron disease (2 papers, 2016). "The most notable among these is the mutations in Vps54 gene leading to a motor neuron disease similar to mild SMA and defects in male reproductive organ development." (PMID 26830971, 2016). "A mutation in Vps54 in mice (“Wobbler” mouse) which causes a destabilization of the GARP complex has been reported to cause defective spermiogenesis and motor neuron disease, while a Vps54 null mutation leads to embryonic lethality." (PMID 26973835, 2016).
age-related macular degeneration (1 paper, 2023). Age-related loss of vision in the central portion of the retina (macula), secondary to retinal degeneration. "VPS54 is reported to be associated with Retinitis pigmentosa; IQGAP1 is reported to regulate choroidal vascularization in Age-Related Macular Degeneration; NMB is involved in RPE homeostasis regulation; MC5R is reported to regulate lacrimal gland function." (PMID 37359372, 2023).
amyotrophic lateral sclerosis (1 paper, 2016). Amyotrophic lateral sclerosis (ALS) is a neurodegenerative disease characterized by progressive muscular paralysis reflecting degeneration of motor neurons in the primary motor cortex, corticospinal tracts, brainstem and spinal cord. "Mutations in VPS54 and VPS52 lead to neurological disorders in mice that have been studied as models of the human diseases amyotrophic lateral sclerosis (ALS) and the seizure disorder high-pressure nervous syndrome, respectively." (PMID 27191843, 2016).
endometritis (1 paper, 2022). An acute or chronic, usually bacterial infectious process affecting the endometrium. "Compared with the control group, circ-Chsy1, circ-Gm49339, mmu_circ_0001853 were significantly overexpressed (p < 0.01), and circ-Vps54 and mmu_circ_0000668 were significantly underexpressed in the endometritis group (p < 0.01)." (PMID 35744807, 2022).
motor neuron degeneration (1 paper, 2013). "The autosomal recessive-mutation was soon linked to motor neuron degeneration and is caused by a point mutation in the Vps54 gene." (PMID 23539154, 2013).
pancreatic cancer (1 paper, 2025). "A notable exception is VPS54, with opposite effects in BOCA and PACA (pancreatic cancer)." (PMID 39975298, 2025).
retinitis pigmentosa (1 paper, 2023). Retinitis pigmentosa (RP) is an inherited retinal dystrophy leading to progressive loss of the photoreceptors and retinal pigment epithelium and resulting in blindness usually after several decades. "Moreover, VPS54 is reported to be part of RP28, a locus associated with recessive retinitis pigmentosa." (PMID 37359372, 2023).
spinal muscular atrophy (1 paper, 2021). A motor neuron disease that affect the muscles, and characterized by muscle weakness and atrophy resulting from progressive degeneration and irreversible loss of the anterior horn cells in the spinal cord (i.e., lower motor neurons) and the brain stem nuclei. "Mutations in the gene encoding the VPS54 subunit, which lead to a drastic reduction in levels of VPS54 and disturb the GARP complex assembly, result in spinal muscular atrophy in the “wobbler” mouse that is considered as a model for ALS." (PMID 34359848, 2021).
neurodegenerative disease (1 paper, 2015). A disorder of the central nervous system characterized by gradual and progressive loss of neural tissue and neurologic function. "Interestingly, the disruption of the GARP subunit Vps54 in mice leads to a ‘wobbler’ phenotype, indicative of neurodegenerative disease sharing characteristics of ALS, including progressive motor degeneration and motor neuron loss." (PMID 26357016, 2015).
VPS54 also shares sentences with these, for which no sentence is quoted: Globozoospermia (2 papers); acephalic spermatozoa syndrome (1); COVID-19 (1); dry eye (1); fibrosarcoma (1); neurological disorders (1); pontocerebellar hypoplasia type 2E (1); seizure disorder (1).